C5orf22 (chromosome 5 open reading frame 22)
Synonyms: FLJ11193
Tractability: PROTAC: ubiquitination databases record sites on it; its protein half-life has been measured.
Gene: Protein-coding gene on chromosome 5 (31,532,287 to 31,555,053, forward strand). Ensembl gene ENSG00000082213.
Subcellular location (Human Protein Atlas): Nuclear membrane
Gene Ontology:
Molecular function: protein binding
Genetic constraint (gnomAD): Loss-of-function variants: 27 observed, 40.28 expected, observed/expected ratio (o/e) 0.67, 90% interval 0.49 to 0.92. The synonymous counts are far from expectation, so gnomAD's model fits this gene poorly and the ratio says little. Missense variants: 437 observed, 489.42 expected, observed/expected ratio (o/e) 0.89, 90% interval 0.82 to 0.97. Synonymous variants: 132 observed, 172.47 expected, observed/expected ratio (o/e) 0.77, 90% interval 0.66 to 0.88.
Homologues: Orthologues: chimpanzee C5H5orf22 (99% identical), macaque C6H5orf22 (97% identical), dog C5orf22 (89% identical), pig C5orf22 (88% identical), guinea pig C5orf22 (83% identical), mouse 6030458C11Rik (78% identical), rat C2h5orf22 (75% identical), rabbit C5orf22 (74% identical), tropical clawed frog c6h5orf22 (64% identical), zebrafish C2H5orf22 (55% identical), Drosophila melanogaster MESR6 (30% identical).
Diseases named in the same sentence as C5orf22 in open-access papers:
C5orf22 is named in the same sentence as 2 diseases in open-access papers, as found by Europe PMC text mining. Sharing a sentence is not in itself a finding about the gene and the disease. The quoted sentences say what the papers report.
tumor (2 papers, 2017 to 2024). "For example, the peptides RVQILQILK (DIEXF) and STDLPILLK (C5orf22) were identified in 9 and 7 tumor patients, respectively." (PMID 39835134, 2024). "The peptides with increased presentation in SK-Mel-28 dr cells derived from EIF4B, FAM20B, LDHB, CYCS, C5orf22, RCAN1 and DIEXF and were recurrently identified in TvHdb in a variety of tumor patients." (PMID 39835134, 2024).
C5orf22 also shares sentences with these, for which no sentence is quoted: lung carcinoma (1 paper).